BRCA2 (BRCA2 DNA repair associated)
Diseases named in the same sentence as BRCA2 in open-access papers (continued):
Sharing a sentence is not in itself a finding about the gene and the disease.
breast cancer (continued). "The presence of BRCA1/BRCA2 gene mutations is associated with a cumulative risk of breast cancer at age of 70 of more than 60%, and the probability of developing this malignant tumor throughout life varies in the range of 41–90%." (PMID 35626173, 2022). "Mutations of the BRCA1 and BRCA2 genes in the germline were considered resources of genetic susceptibility for breast cancer." (PMID 36713553, 2022). "In conclusion, in our study, we identified 19 BRCA gene mutational variants, namely 8 BRCA1 variations and 11 BRCA2 variations, 4 of which were found in both groups of patients (ovarian and breast cancer patients)." (PMID 35409996, 2022). "Increased fat mass and dysmetabolism are recognized to promote breast cancer risk in the general population but there is evidence to indicate a greater impact in BRCA2 carriers, and diet has also been shown to influence BRCA penetrance." (PMID 35362092, 2022). "Mutations in the BRCA gene, BRCA1 and BRCA2 is the most common germline aberrations associated with breast cancer having a collective 70% lifetime risk of developing breast cancer." (PMID 36185256, 2022). "BRCA1 and BRCA2 are tumour suppressor genes that are strongly associated with the early development of breast cancers in both, men, and women, but with distinct differences." (PMID 35804947, 2022). "Mutations in BRCA2 gene increase the risk for breast cancer and for other cancer types, including pancreatic and prostate cancer." (PMID 35734584, 2022). "The CPC plays a role in cell cycle progression and is a prognostic marker of breast cancer arising from BRCA2 mutation." (PMID 35845599, 2022). "Germline mutations of BRCA1 and/or BRCA2 are observed in more than 5% of all breast cancer cases and approximately 13% of basal-like breast cancer (BLBC) cases." (PMID 36209184, 2022). "This was found by using genetic markers to test for BRCA1 and BRCA2 mutations in families from the Breast Cancer Linkage Consortium (BCLC)." (PMID 35740092, 2022). "Carriers of BRCA1 and BRCA2 variants have cumulative breast cancer risks of 72% and 69%, respectively, and cumulative ovarian cancer risks of 44% and 17%, respectively, up to the age of 80 years, which is remarkably higher than those of the general population." (PMID 35627717, 2022). "The impact of RRBSO in patients with BRCA1 and BRCA2 mutation with TN breast cancer in stage I/II increased with age." (PMID 36580360, 2022). "Inheritance of a BRCA1 or BRCA2 mutation greatly increases lifetime risk of breast cancer and ovarian cancer." (PMID 35625955, 2022). "The cumulative risk of developing breast cancer is 69% and developing ovarian cancer is 17% for BRCA2 mutation carriers." (PMID 36361862, 2022). "To date, BRCA1/2 has been very well studied in breast cancer and gynecological oncology, and BRCA2 mutation carriers have been described to be significantly associated with an elevated risk for prostate cancer, colorectal cancer and urothelial carcinoma." (PMID 35372080, 2022). "Most carriers of the pathogenic variant of BRCA1 or BRCA2 with luminal breast cancer in stage I-II (unilateral breast cancer) benefited from RRBM-RRBSO." (PMID 36580360, 2022). "In this study, 454 carriers of mutations in the BRCA1 gene and 273 carriers of mutations in the BRCA2 gene were included under 50 years of age, and 261 had a personal history of breast cancer." (PMID 35805026, 2022). "Oncoprint analysis of the Foundation Medicine dataset also showed that BRCA1 and BRCA2 mutations, and germline and somatic mutations, were mutually exclusive in ovarian cancer and breast cancer." (PMID 34979999, 2022). "Patients with positive expression of the BRCA1 and BRCA2 genes have about an 80% risk of developing breast cancer later in life, mainly around pre-menopausal age." (PMID 35950060, 2022).
breast cancer (continued). "By contrast, patients with breast cancer aged over 49 years with the BRCA2 pathogenic variant in exons 12-25 in stage I who underwent RRBM + RRBSO had an almost similar impact on survival compared with those who underwent RRBSO alone." (PMID 36580360, 2022). "BRCA1 and BRCA2 mutation carriers have a very high risk of breast cancer and ovarian cancer by age 70, at 47–66% and 40–57%, respectively, and of other malignancies, including PC." (PMID 35761384, 2022). "Further, it has been revealed that BRCA1-related tumors profile resembles the TNBC subtype, while the profile of the BRCA2-associated tumor correlates to luminal-like breast cancers, particularly the Luminal B subtype." (PMID 35145999, 2022). "Oral poly (ADP-ribose) polymerase inhibitor olaparib in patients with BRCA1 or BRCA2 mutations and advanced breast cancer: a proof-of-concept trial." (PMID 36197199, 2022). "Germline mutations in both the BRCA1 and BRCA2 genes are found in hereditary breast and ovarian cancers and account for around 7% of breast cancers with a predisposition toward TNBC status." (PMID 35884530, 2022). "WAP-Cre and MMTV-Cre mice have been able to generate hereditary breast cancer models specifically by modeling the heterozygous mutations observed in the BRCA1/BRCA2 genes." (PMID 35186735, 2022). "Two high-penetrance genes (BRCA1 and BRCA2) are responsible for about 16% of the familial risk of breast cancers and associated with a 60–80% lifetime risk of developing breast cancer." (PMID 34128142, 2022). "For example, a male with prior prostate cancer, who possessed a germline BRCA2 mutation and a significant family history for breast cancer, was subsequently diagnosed with MBC and underwent curative mastectomy." (PMID 35804947, 2022). "Again, in the seven patients with a germline BRCA2 mutation, the onset of breast cancer always preceded OC diagnosis, with a median age of 52 years and 66 years, respectively." (PMID 36555431, 2022). "Metastatic breast cancer patients with a germline BRCA1 or BRCA2 mutation treated with PARPi have better outcomes in terms of PFS compared to standard chemotherapy." (PMID 35740616, 2022). "Cultural social roles associated with gender and communication processes are linked to the equation that BRCA1 and BRCA2 are «genes responsible for breast cancer» (and “only women have breasts”)." (PMID 35303741, 2022). "Breast cancer susceptibility gene 2 (BRCA2) is the main gene associated with hereditary breast cancers." (PMID 36397405, 2022). "Cancer is a disease of the genome, therefore, its development has a clear Mendelian component, demonstrated by well-studied genes such as BRCA1 and BRCA2 in breast cancer risk." (PMID 35459932, 2022). "The lifetime risk for breast cancer in males with the pathogenetic variants of BRCA2 is 8.9%, 80–100 times higher than for the general population." (PMID 35454911, 2022). "At present, the best individualised breast cancer risk assessments in constitutional BRCA1/BRCA2 carriers are estimated using a validated programme such as CanRisk." (PMID 36068545, 2022). "Our study showed that it is mandatory to consider the complex interplay between the type of BRCA1 and BRCA2 pathogenic variants, age at primary breast cancer diagnosis, breast cancer subtype and stage, and systemic treatment received." (PMID 36580360, 2022). "Women who carry pathogenic variants in BRCA1 (OMIM 113705) and BRCA2 (OMIM 600185) have greatly increased risk of developing breast cancer." (PMID 36203093, 2022). "They found that DNA-PKcs inhibition in BRCA2-deficient breast cancer with acquired PARPi resistance efficiently restored drug sensitivity by impairing fork slowing." (PMID 36359297, 2022). "BRCA2-001/Short is expressed more frequently in recurrences and associated with reduced overall survival in breast cancer (87 vs. 121 months; Hazard Ratio = 2.5 [1.18–5.5])." (PMID 36344544, 2022).
breast cancer (continued). "Breast cancers harboring germline mutations in either BRCA1 or BRCA2 are highly sensitive to PARP inhibitors, and thus, inhibiting PARPs has become a therapeutic strategy for targeting BRCA1/2-mutated cancer cells." (PMID 36209184, 2022). "We elucidated clinical characteristic and genomic analyses in germline BRCA1 or BRCA2 mutated breast cancer in Korean women." (PMID 35151316, 2022). "Secondly, all cases had a BRCA1 mutation, while two controls had a high risk of developing breast cancer due to a familial predisposition and the other control was identified with a BRCA2 mutation." (PMID 36293255, 2022). "The mean age of patients who carried deleterious variant in BRCA1/BRCA2 was 39 years and 8 months compared to 47 years and 3 months among women who carried a deleterious variant in other breast cancer susceptibility genes." (PMID 35039564, 2022). "The mean age of patients who carried deleterious variant in BRCA1/BRCA2 was 39 years and 8 months compared to 47 years and 3 months among women who carried a deleterious variants in other breast cancer susceptibility genes." (PMID 35039564, 2022). "The study aims to develop a personalized risk management decision support tool for carriers of a pathogenic variant (BRCA1 or BRCA2) who underwent breast-conserving therapy for unilateral early-stage breast cancer." (PMID 36580360, 2022). "Canines have a high incidence of mammary tumors, and several mutations have been detected in BRCA2 and RAD51." (PMID 36548864, 2022). "Previous studies have shown that people who carry the breast cancer susceptibility gene 1 (BRCA1) or breast cancer susceptibility gene 2 (BRCA2) variants are predisposed to breast cancer." (PMID 36540803, 2022). "Women carrying a pathogenic germline BRCA1 or BRCA2 mutation have life-time breast cancer (BC) risks up to 75%, and are often diagnosed with BC at a relatively young age." (PMID 35507134, 2022). "We identified 17 BRCA2 variants (1 variant was discovered in both ovarian and breast cancer patients, 6 distinct variants were discovered in BC patients, and 10 distinct variants were discovered in OC patients)." (PMID 35409996, 2022). "BRCA1 and BRCA2 gene mutations are responsible for 5% of breast cancer (BC) and 10–15% of ovarian cancer (EOC)." (PMID 36307994, 2022). "Meanwhile, those with BRCA2 were associated with earlier age at diagnosis of female breast cancer (−5.7 years) and prostate cancer (−2.2 years)." (PMID 35420638, 2022). "BRCA2 variants typically cause ER-positive luminal subtypes, showing slow proliferation with low grade clinical aggression of breast cancer." (PMID 35008774, 2021). "At the mid-1990s, the role of BRCA1 and BRCA2 mutations in elevating breast cancer risk was considered." (PMID 33805996, 2021). "Among them, we highlight the rs11571707, rs144848, and rs11571769 variants of the BRCA2 gene due to their association with the hereditary breast cancer onset." (PMID 33499154, 2021). "The knowledge about BRCA1 and BRCA2 variants is critical to establish public policies for hereditary breast cancer screening in Amerindian groups and populations admixed with them, such as the Brazilian population." (PMID 33499154, 2021). "The BRCA2-p.K1568N mutation detected in BCX1 tumors is currently considered of unlikely significance for familial breast cancer risk as a somatic mutation." (PMID 34524841, 2021). "In a large-scale breast cancer GWAS study in 2013, the BRCA2 c.9976A > T variant was shown to be a low penetrance risk allele for breast cancer." (PMID 34439109, 2021). "A study including 1504 patients with germline BRCA1 or BRCA2 mutations showed that chemoprevention using tamoxifen is associated with a 50% reduction in the risk for developing contralateral breast cancer." (PMID 34206661, 2021).
breast cancer (continued). "Molecular markers, like BRCA1 or BRCA2 (breast cancer gene 1 or 2) germline mutations, are indicators of possible basal-like breast cancer development and are used to determine potential risk and guide treatment." (PMID 34521857, 2021). "Variants of uncertain significance in the breast cancer susceptibility gene BRCA2 represent 50–80% of the results from genetic testing." (PMID 34359619, 2021). "Molecular genetic studies have elucidated breast-cancer susceptibility genes 1 and 2 (BRCA1 and BRCA2) as two major predisposing genes for breast cancer." (PMID 34206661, 2021). "We identified loss of heterozygosity as an underlying mechanism by which BRCA2 expression levels are reduced in canine mammary tumors." (PMID 33407082, 2021). "Pathogenic attenuations in either BRCA1 or BRCA2 account for 25–40% of familial breast cancers and up to 10% of all breast cancers." (PMID 35008774, 2021). "The breast cancer susceptibility gene BRCA2 encodes a multifunctional protein required for the accurate repair of DNA double-strand breaks and replicative DNA lesions." (PMID 34359619, 2021). "Prophylactic mastectomy is the removal of the contralateral breast in a patient diagnosed with breast cancer or someone at a higher risk of developing breast cancer (BRCA2 mutation carrier, recurrent breast cancer), in which case both breasts are removed." (PMID 34725599, 2021). "The principle of inhibiting DNA repair genes has been proposed for cells that carry mutations in the breast cancer susceptibility genes BRCA1 or BRCA2 as a possible cancer drug target." (PMID 34305605, 2021). "Anticipation effects have also been reported from this study cohort where daughters of mother-daughter pairs with the BRCA2 999del5 germline mutation have been shown to be diagnosed with breast cancer on average 10 years younger than the mothers." (PMID 35052422, 2021). "In humans, germline heterozygous BRCA1 mutations cause the highest risk and earliest onset of breast cancer, followed by BRCA2 and then PALB2 mutations." (PMID 33893322, 2021). "Germline P/LP variants in BRCA1 and BRCA2 accounted for 80% of P/LP variants found in breast cancer and 57% of P/LP variants found in ovarian cancer." (PMID 33649982, 2021). "This single BRCA2 mutation accounts for 7–8% of female breast cancers and 40% of male breast cancers there." (PMID 34830851, 2021). "Evidenced-based management of individuals with confirmed high penetrance pathogenic variants such as BRCA1 and BRCA2 can result in earlier detection of breast cancer when early and timely screening using optimal detection methods is applied." (PMID 33507482, 2021). "Among previously published literature, breast cancer risk was elevated for BRCA2 c.9976A>T carriers when compared to a control population in three reports." (PMID 33672545, 2021). "In conclusion, we found that oophorectomy is associated with a reduced risk of death from breast cancer in BRCA2 carriers with breast cancer and should be considered in the treatment plan." (PMID 33597716, 2021). "The risk of male breast cancer is also increased in the male carriers of such variants, particularly those in BRCA2, where the lifetime risk is approximately 8–10% when compared to BRCA1, where the risk is in the order of 1%." (PMID 34771713, 2021). "In two of the cases, we show that despite extensive and variable HRD related CNV profiles BRCA2 mutant breast cancers retain shared fixed variants targeting a discrete set of genes throughout the tumor." (PMID 34011996, 2021). "While none of the non-carriers developed contralateral breast cancer, both men with bilateral breast cancer in our cohort were carriers of deleterious variants in BRCA2 (p = 0.059)." (PMID 33891299, 2021). "We are, hence, currently preparing a meta-analysis in which we will examine the effect of BRCA1 and BRCA2 mutations on the occurrence of breast cancer." (PMID 33925599, 2021).
breast cancer (continued). "A clinical trial (NCT00494234) for a poly adenosine diphosphate-ribose polymerase (PARP) inhibitor, olaparib, in patients with BRCA1 or BRCA2 mutations and advanced breast cancer, provided an impressive ORR of 44%." (PMID 34396843, 2021). "BRCA-1 associated breast cancers are more likely to be triple negative (TNBC), whereas BRCA-2-associated breast cancers are often hormonally driven and human epidermal growth factor receptor 2 (HER2)-negative." (PMID 34573353, 2021). "More interestingly, methylation levels of 38 CpGDMs were able to separate primary tumor tissue from normal breast tissue in patients with familial breast cancer mutation in the BRCA2 gene (pairs N4/T4, N5/T5, N11/T11)." (PMID 33145876, 2021). "For a few years, PARPi has shown promising activity as a chemotherapeutic agent in BRCA1- or BRCA2-associated breast cancers, and in combination with chemotherapy in triple-negative breast cancer." (PMID 34829741, 2021). "Although BRCA1 and BRCA2 are the most mutated genes, additional genes associated with hereditary breast cancer are emerging." (PMID 34046273, 2021). "After a diagnosis of breast cancer, however, the measured relative telomere length in blood cells of BRCA2 999del5 mutation carriers was found to be significantly shorter than among non-carriers." (PMID 35052422, 2021). "Germline mutations in BRCA1 and BRCA2 account for around 25% of familial breast cancer clustering and 5–10% risk of all breast cancer cases." (PMID 34207556, 2021). "Female breast cancer patients with a BRCA1 or BRCA2 pathogenic variant have an increased risk of a second primary breast cancer and/or ovarian cancer." (PMID 33319336, 2021). "Breast cancer 2 early onset (BRCA2) is a tumor suppressor gene encoding a protein that contributes to homologous recombination (HR)-mediated DNA repair." (PMID 33407082, 2021). "The reported risk of ovarian and breast cancers in women with a BRCA2 mutation is 10–27% and 45–85%, respectively." (PMID 35011855, 2021). "A group from Aviano, Italy, also reported this variant as recurrent in northeast part of Italy and suggested an association between this splice-site BRCA2 variant and risk of breast cancer in males." (PMID 33891299, 2021). "The breast cancer susceptibility gene BRCA2 is another crucial gene for HR in eukaryotes and was first identified in humans." (PMID 33916151, 2021). "It is important to confirm that oophorectomy is helpful in the treatment of breast cancer in patients with a BRCA2 mutation." (PMID 33597716, 2021). "Male BRCA1 and BRCA2 carriers are also at an increased risk of breast cancer with risk estimates of ~1–5% and 5–10% respectively, compared with the general male population where the life-time risks are ~0.1%." (PMID 34439109, 2021). "Other risk factors associated with male breast cancer are mutations in the BRCA2 gene and radiation exposure." (PMID 33725931, 2021). "In our study, this variant was found in two sisters with breast cancer at ages 44 and 51, and both carry the BRCA2 p.Val875Leu likely pathogenic variant." (PMID 33558524, 2021). "Somatic mutations of BRCA1 and BRCA2 in breast cancer are positively correlated with cancer survival." (PMID 34711195, 2021). "Of note is that BRCA2 999del5 breast cancer cases with wild-type allelic loss had significantly worse breast cancer specific survival compared to cases that remained the wild-type allele." (PMID 35052422, 2021). "Primary prevention of breast cancer is not yet a reality except by undergoing prophylactic mastectomy for those who have the BRCA1 or BRCA2 gene mutation, known to cause breast cancer." (PMID 34437623, 2021). "Age, mutations in Breast Cancer Gene 1 or 2 (BRCA1 or BRCA2) genes, and dense breast tissue are the highest risk factors." (PMID 34638847, 2021).